ENSG00000284431 (novel protein)
Gene: Protein-coding gene on chromosome 22 (40,346,529 to 40,410,054, forward strand). Ensembl gene ENSG00000284431.
Genetic constraint (gnomAD): Missense variants: 92 observed, 81.86 expected, observed/expected ratio (o/e) 1.12, 90% interval 0.95 to 1.34. Synonymous variants: 41 observed, 33.07 expected, observed/expected ratio (o/e) 1.24, 90% interval 0.96 to 1.61.